NRP1 (neuropilin 1)
Diseases named in the same sentence as NRP1 in open-access papers (continued):
Sharing a sentence is not in itself a finding about the gene and the disease.
cancer (continued). "Other membrane receptors such as Neuropilins (NRP1) or Plexins are also important regulators of cancer progression through signaling pathways involving actin cytoskeleton remodeling." (PMID 32351895, 2020). "Neuropilin-1 (NRP1) is a transmembrane receptor that promotes the progression of cancer by interacting with VEGF/VEGFR2 and EGFR." (PMID 32708604, 2020). "NRP-1 is often expressed in carcinoma (in particular tumors of epithelial origin) including lung, chest, prostate, pancreas, and clone carcinoma." (PMID 33149867, 2020). "The O-linked glycosylation of NRP1 at Ser612 plays an important role in the modulation of VEGF signaling, cell proliferation and migration and cancer invasion." (PMID 31420553, 2019). "The involvement of VEGF165/NRP-1 interaction in cancer pathology makes its inhibition an interesting approach for finding novel anticancer therapies." (PMID 31064153, 2019). "PDGF-D can bind to NRP1 and induce the formation of a holoreceptor with PDGFRβ, thereby stimulating proliferation in fibrotic processes and various cancers." (PMID 30717262, 2019). "We developed a high‐throughput, combined quantitative detection system for Nrp1 and Nrp2 based on liquid chip technology as a potential new method for the early detection, monitoring, and clinical prognosis prediction of cancer." (PMID 30758083, 2019). "The CendR motif (R/KXXR/K) provided high affinity of CRGDK to neuropilin-1 leading to an increase in drug penetration through the endothelium to the cancer cells." (PMID 30691192, 2019). "The resulting construct CPL-K (CP-linker-“Kill”) binds to NRP1 in cancer cells and disrupts NRP1 complex formation with PlexA1 as well as downstream Akt survival signaling." (PMID 31652529, 2019). "The VEGF/NRP-1 pathway is involved in the proliferation of cancer cells by activating Akt, leading to sequential downregulation of p27, which binds to CDK2 and suppresses the activity of CDK2/cyclin E complex." (PMID 31572065, 2019). "Overexpression of NRP-1 was reported to promote the proliferation of cancer cells, which probably suggested that the cell damage effect of 7.5 μM SSd was antagonized by the proliferation promotion of upregulating NRP-1." (PMID 30978940, 2019). "NRP1 acts as a signaling hub on the cell surface and plays multifaceted roles in multiple cancers including CRC5,22." (PMID 31420553, 2019). "Among the signal transduction pathways involved in adaptive cancer response to therapy are tyrosine kinase receptors (RTKs) regulated by NRP1, such as EGFR and IGF1-R, and intracellular effectors, such as PI3K/AKT, MAPK/ERK or NF-κB." (PMID 31027288, 2019). "To achieve such a find and kill approach we selected two types of peptides that previously have been demonstrated to have targeting (ATW-NRP1]) and inhibitory functions (MTP-NRP1) towards NRP1, a key molecule in promoting cancer growth." (PMID 31652529, 2019). "Increased expression of Nrp-1 on Treg in cancer enhances immune suppression through interactions with DCs." (PMID 31681327, 2019). "NRP1 is overexpressed in a range of human cancers including CRC, and increased expression of NRP1 is associated with poor patient prognosis." (PMID 31420553, 2019). "The authors verified that the presence of the E16G6RGDK peptides on the surface of the siRNA/AD micelles was indeed effective in specifically targeting cancer cells via dual binding with the designated target receptors ανβ3integrin and Nrp-1." (PMID 31295912, 2019). "We have previously demonstrated that NRP-1 acts as a multiple co-receptor to promote the proliferation of cancer cells by activating the VEGF/VEGFR2 (VEGF receptor 2), EGF/EGFR (EGF receptor) and HGF/c-Met pathways." (PMID 31572065, 2019). "Sunitinib, a multi-targeted tyrosine kinase inhibitor, also induced evasive adaption in cancer cells through an alternative neurophilin 1(NRP-1)-mediated signaling." (PMID 31781495, 2019).
cancer (continued). "The levels of four cancer-related serum biomarkers (prostate specific antigen, neuropilin-1, osteopontin, and matrix-metalloproteinase 7) decreased, as measured by immunoassay, when serum samples were stored for one to two weeks in dextran-based matrix." (PMID 31490977, 2019). "Here, we studied the pattern of VEGR2 and NRP1 expression and the potential for complex formation in several different human cancers." (PMID 30027561, 2018). "NRP-1 is involved in cell survival and proliferation and has been reported to be over-expressed in various cancers, which have also been correlated with poor prognosis." (PMID 29632646, 2018). "Nrp1 has been shown to bind TGFβ and LAP-TGFβ and amplify signaling associated with these ligands in cancer cells via co-reception with TGFβRI/II." (PMID 32914058, 2018). "The potential benefit of blocking NRP1 function has been tested using neutralizing anti‐NRP1 antibodies on human cancer‐xenografted mice." (PMID 30027561, 2018). "NRP1+ Tregs are greatly enriched in cancer patient PBL and TIL across numerous malignancies, and high NRP1 expression on intratumoral Tregs negatively correlates with disease-free survival in HNSCC." (PMID 30400822, 2018). "The use of in situ PLA to directly show the presence of VEGFR2/NRP1 complexes in human cancer has challenges, for example in deducing the exact localization of the PLA dots." (PMID 30027561, 2018). "Proinflammatory cytokines, such as IFNγ, also drove increased NRP1 expression in a subset of cancer patient samples." (PMID 30400822, 2018). "This small molecule decreased the self-renewal capacity of MB stem cells for the 3 cell lines and reduced the invasive ability of DAOY and D283 stem cells while NRP-1 expression and cancer stem cell markers decreased at the same time." (PMID 29632646, 2018). "We describe a novel association between NRP-1 and TNC expression, an extracellular matrix (ECM) glycoprotein molecule that induces EMT, migration, proliferation and immune modulations in cancer." (PMID 29728077, 2018). "This is the first demonstration that the activation of RhoA is induced by NRP1 alone in cancer cells, although RhoA in endothelial cells has been reported to be activated specifically by NRP1 through the Gq and PI3 kinase pathway for cell migration." (PMID 29659486, 2018). "NRP1 expression is also detected on alveolar macrophages adjacent to the cancer margin in patients with lung cancer." (PMID 29067024, 2017). "To understand the differential role of NRP1 in tumorigenesis process, we utilized cells from two different cancer types, pancreatic and lung, each containing either wild type KRAS (KRASwt) or mutant KRAS (KRASmt)." (PMID 29018205, 2017). "Here, we found that extracellular VEGF bound to NRP1 in the cancer cell membrane, which activated Cdc42 to recruit intra-mitochondrial PHB to the front ends of CRC cells." (PMID 29100316, 2017). "Correspondingly, our data indicate that NRP1 knockdown in KRASmt cancer cells (PANC-1, A549) promotes tumorigenesis, whereas NRP1 down regulation in KRASwt cells (BxPC-3, H226) inhibits tumorigenesis." (PMID 29018205, 2017). "In cancer cells harboring KRASmt, NRP1 down regulation promotes tumorigenesis through the suppression of SMAD2 pathway." (PMID 29018205, 2017). "Our findings demonstrate that the effects of NRP1 knockdown in cancer cells are dependent on the genetic status of KRAS." (PMID 29018205, 2017). "Taken together, these findings place NRP1 as a potential candidate for targeting Tregs in the treatment of diseases such as cancer." (PMID 29067024, 2017). "We highlight cancer-specific down regulation of NRP-1, SNAI1 and SEMA4A in PBMCs with a further decrease of SNAI1, SEMA4A, VEGFR3 and PLXNA1 in patients with advanced disease." (PMID 28607365, 2017). "On the other hand, several previous studies have implicated NRP1 and WNT signaling in various types of cancer growth and progression, which are consistent with the expected characteristics of miR-148a target genes." (PMID 26967387, 2016).
cancer (continued). "NRP1 is found both on the cell surface of a number of cancer cells, and can be rapidly internalized." (PMID 27486976, 2016). "It remains to be investigated why NRP1 has opposing roles in TGFβ signalling in endothelial cells versus smooth muscle or cancer cells." (PMID 26923176, 2016). "It is known that NRP1 can affect various cellular functions, such as migration or proliferation, which are relevant to cancer progression." (PMID 27798666, 2016). "Some studies have shown that Nrp-1 has a co-receptor function for TGF-β1 on the membrane of cancer cells and enhances responses to both latent and active TGF-β14." (PMID 27075020, 2016). "NRP-1 is also implicated in the activation of HGF-induced signaling and cellular responses in cancer cells." (PMID 26795388, 2016). "The VEGF/NRP-1 pathway is also involved in cancer cell proliferation by activating Akt, leading to sequential p27 downregulation." (PMID 26795388, 2016). "PC3 and MDA-MB-231 cancer cells are known to constitutively express a significant level of NRP1 and to respond to NRP1-mediated signaling." (PMID 27798666, 2016). "Specific inhibition of NRP-1 has been shown to suppress the growth and metastasis of several types of cancer cells." (PMID 26795388, 2016). "NRP1-FS is known to regulate cell functions involved in cancer progression such as proliferation, migration or anchorage-independent growth." (PMID 27798666, 2016). "The frequency of NRP-1+ AMs in lung tissue adjacent to the cancer margin was significantly higher than the frequency of NRP-1+ AMs in inflamed lung and lung tissue remote to the cancer nest." (PMID 26900851, 2016). "The mechanisms for the role of NRP-1 in cancer progression rely on its interactions with several key signaling pathways in cancer cells." (PMID 26795388, 2016). "Consistent with our results, NRP1 functions to protect cancer cells from stress-induced apoptosis and mediates their spreading and membrane ruffling in vitro, which are crucial processes in metastasis." (PMID 26967387, 2016). "The role of the naturally occurring NRP1-Δ7 was therefore evaluated in functional assays relevant to cancer biology." (PMID 27798666, 2016). "In this study, we found that aberrant NRP-1 expression was positively associated with enhanced levels of NEDD9, a protein linked with increased metastases in multiple human cancers." (PMID 26701889, 2016). "Our findings reveal a novel mechanism underlying the anti-metastasis function of NDGA and indicate the potential value of NDGA in NRP1 targeting therapy for selected subtypes of cancer." (PMID 27863391, 2016). "In inflamed lung, the number of NRP-1+ AMs was higher than that of NRP-1+ AMs in lung tissue remote to the cancer nest." (PMID 26900851, 2016). "It is now known that NRP-1 also acts as multifunctional co-receptors participating in the initiation, growth and metastasis of cancer cells." (PMID 26795388, 2016). "To investigate the biological properties of this isoform, we generated prostatic (PC3) and breast (MDA-MB-231) cancer cells able to express recombinant NRP1-FS or NRP1-Δ7 in a doxycycline-inducible manner." (PMID 27798666, 2016). "In conclusion, this new signaling pathway of VEGF-A/NRP1 induced cancer cell proliferation by forming a GIPC1/Syx complex that activated RhoA to degrade the p27 protein." (PMID 26209534, 2015). "Since NRP-1 is frequently expressed in cancer cells, this NRP-1 activity is being explored for the targeted delivery of therapeutic and diagnostic agents." (PMID 26090340, 2015). "The treatment of cancer cells with the soluble NRP1 B domain or siNRP1 inhibited proliferation in an anchorage-independent manner." (PMID 26209534, 2015). "This peptide interacted with NRP-1 and exhibited anti-angiogenic activity in different in vivo animal models of cancer." (PMID 26090340, 2015). "NRP-1’s role in nervous system development, immunity, and more recently in cancer, has been extensively investigated." (PMID 26239560, 2015).
cancer (continued). "In summary, we proposed a novel signal transduction pathway of VEGF-A/NRP1 that induced cancer cell proliferation by forming a GIPC1/Syx complex that activated RhoA and degraded p27." (PMID 26209534, 2015). "NRP1 has been shown to promote epithelial mesenchymal transition and increase motility of endothelial cells as well as cancer cells by regulating TGF-beta, integrin and HGF/c-Met signaling." (PMID 26097868, 2015). "Currently, VEGF and its receptors VEGFR-1, VEGFR-2, and Neuropilin-1 (NRP-1) are targeted in therapeutic strategies for vascular disease and cancer." (PMID 25873749, 2015). "As a receptor for VEGF, NRP-1 protein is reported to be upregulated in several cancers, whereas the soluble NRP-1 (sNRP-1) is thought to act as an antagonist of signaling complex formation, which can inhibit the function of cell-associated NRP-1." (PMID 25873749, 2015). "In conclusion, this study provided evidence for a new pathway of VEGF-A/NRP1 signaling leading to the proliferation of cancer cells." (PMID 26209534, 2015). "Together, these studies confirmed the effects of iRGD to enhance the intratumoral dissemination and anticancer efficacy in NRP-1-overexpressed cancer models." (PMID 26066322, 2015). "In a recent study utilizing carcinomas, NRP-1 has been detected in blood vessels in more than 98% of cases, whereas its expression in cancer varies depending on the tissue origin, histological sub-type and stage." (PMID 26090340, 2015). "Vascular endothelial growth factor (VEGF) is a key regulator of this process and currently both VEGF and its receptors, VEGFR1, VEGFR2, and Neuropilin1 (NRP1), are targeted in therapeutic strategies for vascular disease and cancer." (PMID 25244320, 2014). "NRP1 is a multifunctional type I transmembrane glycoprotein that plays an important role in axonal extension, angiogenesis, and cancer progression." (PMID 24999732, 2014). "Our results confirm that NRP1 promotes cancer cell migration and invasion in OSCC through induction of the EMT process." (PMID 24999732, 2014). "Immunoreactivity for NRP1 was seen in vessels from normal tissues adjacent to cancer and in 98-100% of carcinomas." (PMID 24708840, 2014). "Monoclonal antibodies and small peptides that block Nrp1-mediated functions are being developed as cancer therapeutics." (PMID 24386482, 2013). "As a receptor for both vascular endothelial growth factors and semaphorin, neuropilin-1 (NRP-1) is reported to be up-regulated in cells of several cancers." (PMID 24053763, 2013). "It is of particular interest that combined anti-VEGF and anti-Nrp1 therapy with monoclonal antibodies was synergistic in mouse models of cancer." (PMID 22948112, 2012). "One of the earliest approaches involved the administration of soluble Nrp1 variants to act as a VEGF trap, and this showed some anti-cancer therapeutic benefits." (PMID 22948112, 2012). "The NRP1 expression, which was observed in the membrane and cytoplasm, was located primarily in cancer nests." (PMID 22926477, 2012). "As a cell surface receptor for VEGF-A neuropilin 1 has been demonstrated to prevent apoptosis in different cell types like neurons, cancer cells or embryonic stem cells." (PMID 23251405, 2012). "Overexpression of NRP-1 in these contexts is thought to enhance cancer cell survival leading to cancer progression, metastatic potential and potential chemoresistance." (PMID 21401950, 2011). "Since then, another peptide targeting NRP1 has been described in various model of cancers cell in vitro." (PMID 24212788, 2011). "Although the role of NRP1 in cancer was largely demonstrated, the precise contribution of NRP2 in oncogenesis was only recently considered." (PMID 21747928, 2011). "While NRP1 was intensively studied for many years and identified as an attractive angiogenesis target for cancer therapy, the NRP2 signaling pathway has just recently been studied." (PMID 24212788, 2011).
cancer (continued). "Interrupting NRP1 functions with mimetic peptides and monoclonal antibodies is being developed in xenograft models of human cancers." (PMID 20085644, 2010). "NRP1 expression was increased from normal/benign glands (0/5) or well-differentiated cancer (1/5) to poorly-differentiated cancers (5/5) and bone metastatic tissues (5/5)." (PMID 20085644, 2010). "Our findings implicate a role for NRP1 in promoting integrin-mediated cancer cell attachment and migration into ECM." (PMID 20087344, 2010). "In the present study, we investigated the effects of the NRP1 antagonist EG3287 on cell proliferation, survival, migration, and adhesion to matrix in the NRP1-expressing carcinoma cell lines, non-small-cell lung A549, kidney ACHN, and prostate DU145 cells." (PMID 20087344, 2010). "EG3287 potently displaced the specific binding of VEGF to NRP1 in carcinoma cell lines and significantly inhibited the migration of A549 and ACHN cells." (PMID 20087344, 2010). "A major conclusion of this study is that the NRP1 antagonist EG3287 markedly inhibits the chemotactic migration of carcinoma lung A549 and kidney ACHN cells." (PMID 20087344, 2010). "Another important finding of our study is that the NRP1 antagonist sensitised carcinoma cells to the clinically important chemotherapeutic agents 5-FU, paclitaxel, and cisplatin." (PMID 20087344, 2010). "EG3287 reduced the adhesion of both lung A549 and kidney ACHN carcinoma cells to ECM, suggesting an important role of NRP1 as a regulator, at least in part, of carcinoma cell attachment to ECM." (PMID 20087344, 2010). "To further investigate the role of NRP1 in carcinoma cell migration, we used RNA interference to knock down NRP1 expression." (PMID 20087344, 2010). "The involvement of NRP1 in carcinoma cell survival and drug response was also examined by downregulation of NRP1 expression." (PMID 20087344, 2010). "Neuropilins, with their ability to rapidly transport Nrp-1-bound compounds into cells, may become a therapeutic target for cancer treatment, allowing for more efficient drug transport into cancer cells." (PMID 40430075, 2025). "Therefore, accurate detection of NRP1 expression is particularly crucial for diagnosing malignant tumors like TNBC and CRC." (PMID 40048021, 2025). "Furthermore, monoclonal antibodies directed against NRP-1 have shown promising antitumor activity by inhibiting cancer cell migration and invasion." (PMID 40430075, 2025). "NRPs upregulated in cancer are highly expressed in macrophages, which show tendency towards the phenotypes of M2-type TAMs, suggesting that NRP1 and NRP2 could be more expressed in M2-type TAMs in ccRCC and SKCM, which could be the specific potential target." (PMID 40134439, 2025). "For example, SNPs that affect the regulatory regions of NRP1 may alter its expression levels and impact cancer progression." (PMID 40277760, 2025). "The development of combination therapies, combining NRP-1 inhibitors with other anti-cancer treatments, could improve the effectiveness of existing treatments." (PMID 40286084, 2025). "The interaction between NRP1 and its ligands, such as Sema3A, can influence the expression and function of immune checkpoint molecules such as programmed cell death protein 1 (PD-1) on T cells, affecting immune responses in cancer and autoimmunity." (PMID 40277760, 2025). "These networks highlight the pathways and processes that NRP1 may regulate or participate in, providing a broader context for its role in cancer." (PMID 40277760, 2025). "Investigating NRP1 as a therapeutic target offers a potential avenue for cancer treatment." (PMID 39083441, 2025). "High VEGF and NRP1 expression were detected in the cytoplasm of cancer cells." (PMID 40277760, 2025). "Additionally, USP37 demonstrated a significant positive relationship with ADORA2A, CD160, TNFSF15 and NRP1 across the majority of cancers." (PMID 40926837, 2025).